HGF (hepatocyte growth factor)
Diseases named in the same sentence as HGF in open-access papers (continued):
Sharing a sentence is not in itself a finding about the gene and the disease.
tumor (continued). "HGF/c-MET signalling has been shown to promote tumour progression, particularly influencing tumour invasiveness and metastatic potential." (PMID 31554791, 2019). "Pro-tumor molecules such as IL-6, IL-8, and HGF secreted by CA-MSCs or their receptors can be blocked to circumvent the pro-tumor effects of the MSC." (PMID 31547627, 2019). "Neutrophils and other immune system cells secrete tumor growth-promoting factors, such as vascular endothelial growth factor, hepatocyte growth factor, interleukin 6, and interleukin 8, and the growth of tumor cells is stimulated." (PMID 30899617, 2019). "Anti-angiogenic therapy can induce tumor hypoxia, and pathways upregulated in the setting of tumor hypoxia, such as sphingosine phosphate and c-Met/HGF signaling, also contribute to TKI resistance." (PMID 30796200, 2019). "Our studies indicated that the concentration of HGF within a KHT tumor is approximately 0.06 ng/mL, which is roughly 100 fold lower than the serum concentrations of the host." (PMID 30719213, 2019). "They examined a panel of 25 SCLC cell lines and xenografts, demonstrating the presence of MET mRNA transcripts and protein expression, but failing to show that these same tumor cells co-expressed its ligand, HGF." (PMID 31547040, 2019). "The hepatocyte growth factor (HGF)/c-Met pathway plays an important role in tumor angiogenesis as well as in the development of resistance to VEGFR inhibition by TKIs." (PMID 31109009, 2019). "Conversely, hypoxic tumor microenvironment can co-activate COX-2 by utilizing the hepatocyte growth factor (HGF) and TGF-β1 autoregulatory loops, and once activated, COX-2 modulates HIF-1α activation." (PMID 31766724, 2019). "Messenger RNA (mRNA) level data on the proteins in the HGF/Met pathway were extracted from the database and for the tumor and healthy tissue samples for each patient." (PMID 31452933, 2019). "Studies have reported that c-Met activation by HGF stimulates multiple signal transduction pathways, which results in cell proliferation, motility, tumor progression, and metastasis." (PMID 31089160, 2019). "After being phosphorylated by its ligand the hepatocyte growth factor (HGF), c-Met can induce a broad spectrum of biological pathways involved in tumor growth." (PMID 30647407, 2019). "In this work, the authors demonstrated that prolonged treatment with these TKIs induced lactate production by tumor cells, which in turn instructed the TME cells to produce hepatocyte growth factor (HGF), enforcing drug resistance and tumor progression." (PMID 31737570, 2019). "EMT can be induced by various signaling pathways (TGF-β, Wnt/β-catenin, Notch, FGF, EGF, and HGF) and hypoxia in tumor progression." (PMID 31399111, 2019). "In summary, heightened HGF/MET signaling is critical for tumor formation and progression in Tpl2 −/− mice." (PMID 30631034, 2019). "The concentration of HGF is clearly important in predicting response to c-Met inhibition in paracrine-activated tumor cells." (PMID 30719213, 2019). "Knockdown of the JNK by siRNA or competitive binding of c-MET receptor by stimulation with HGF-antagonized anti-tumor effects of Tivantinib was observed." (PMID 30850583, 2019). "The main target for secreted HGF were c-Met on the surface of endothelial cells within the tumor, which indicates that the tumor vasculature mainly responds with the resistance to the sunitinib therapy by a shift to the alternative signaling pathway." (PMID 30909397, 2019). "These included human, murine, and canine tumor cell lines, as well as human and murine stromal cells, with HGF normalized as pg/106 cells." (PMID 30719213, 2019). "The hepatocyte growth factor (HGF)/mesenchymal–epithelial transition factor (MET) axis is a further disregulated pathway in cancer which provokes tumor proliferation, as well as therapy escape." (PMID 31013694, 2019).
tumor (continued). "In line with this important finding, we and others have demonstrated that c-Met and HGF play important roles among three compartments in the metastatic bone microenvironments, i.e., tumor cells, osteoclasts, and osteoblasts." (PMID 30658428, 2019). "Our data suggest that concentrations of 25–50 ng/mL HGF strongly activate c-Met in paracrine-activated tumor cells." (PMID 30719213, 2019). "“In immunocytochemical studies of BALF cytospin preparations and tumor specimens from the patients, neutrophils were always HGF-positive”." (PMID 31799175, 2019). "When close to transformed cells in tumoral ducts, CAF support tumor growth by overexpression of hepatocyte growth factor (HGF), heparin-binding epidermal growth factor (HB-EGF), TGF-β and SDF-1/CXCL12." (PMID 31450710, 2019). "Several groups reported a decreased survival rate in cancer patients with an aberrant tumor expression of either MET or its ligand HGF, including SCLC patients." (PMID 31547040, 2019). "HGF/c-Met signalling pathway has many biological functions and can promote tumour proliferation, invasion, metastasis and angiogenesis." (PMID 31137515, 2019). "While many tumor cell lines were insensitive to c-Met inhibition unless in the presence of high exogenous HGF, we identified a number of cell lines that were intrinsically sensitive to the inhibitor." (PMID 30719213, 2019). "Since its first discovery as an oncogene, c-Met and its sole ligand HGF have been postulated to play critical roles in tumor progression, particularly tumor-stromal interactions." (PMID 30658428, 2019). "Rilotumumab (AMG102), a neutralizing antibody against HGF, has shown antitumor activity in vitro and in U-87 MG tumor xenograft models as a single agent." (PMID 31221203, 2019). "Here, in vitro, BsAb-5 inhibits HGF-mediated tumor development, including proliferation, migration, and apoptosis, serving as an inhibitory c-MET antibody." (PMID 29187584, 2019). "Ongoing efforts have identified an important role of HGF/c-Met signaling in the promotion of tumor angiogenesis, growth and metastasis of HB." (PMID 31781561, 2019). "Given that HGF is a stromal factor whose receptor, c-Met, is expressed in carcinoma cells, the c-Met/HGF axis was investigated in the context of tumor-stromal interactions." (PMID 30658428, 2019). "While many studies have quantified HGF in serum, as well as tumor homogenates, there have been no studies providing a volumetric assessment of HGF within a tumor." (PMID 30719213, 2019). "While these findings are very preliminary, they do caution against assumptions of elevated intra-tumor HGF concentrations." (PMID 30719213, 2019). "While the paracrine-activated tumor cell lines showed a response to the c-Met inhibitor only in the presence of high levels of HGF, autocrine-activated tumor cell lines were intrinsically sensitive to the drug." (PMID 30719213, 2019). "Overexpression of c-Met and HGF are also thought to result in resistance of tumour cells to chemotherapy and radiotherapy, correlating with development of distant metastases and shorter metastasis-free survival." (PMID 31613934, 2019). "In vascular endothelial cells, HGF stimulates β1 integrin recycling to promote cell spreading, focal adhesion formation, cell migration and tumor angiogenesis." (PMID 31109009, 2019). "HGSOC ascites are a pro-inflammatory tumor environment that contains a variety of cytokines, chemokines and growth factors including leptin, hepatocyte growth factor (HGF), IL-6, and CCL18." (PMID 31039761, 2019). "This is reminiscent of tumor cell mobilization in response to EMT induction by HGF and other mediators." (PMID 31096701, 2019). "Aberrant HGF/c-Met signaling in OSCC promotes tumor progression by increasing the invasive capacity by acquiring an elongated spindle-like morphology." (PMID 29758011, 2018).
tumor (continued). "In active MM plasma cells secrete VEGF and FGF-2 that induce the cells of the tumor microenvironment to secrete their own VEGF, FGF-2, and HGF, able to recruit and activate the MM-associated macrophages." (PMID 30002349, 2018). "Baseline angioprotein-1 and hepatocyte growth factor showed a direct correlation with tumor volume whereas changes in vascular cell adhesion molecule 1 showed significant correlations with 18F-fluorothymidine (FLT) positron emission tomography (PET)." (PMID 29398577, 2018). "HGF/c-Met is closely related to Wnt/β-catenin signaling, and promotes tumor proliferation, invasion, and metastasis by modulating this signaling pathway." (PMID 29455668, 2018). "HGF produced by tumor and stromal cells acts as a multifunctional cytokine that plays an important role in cancer progression by promoting proliferation, survival, motility, angiogenesis, invasion and metastasis." (PMID 30352967, 2018). "Activated CAFs in the tumor microenvironment not only helps tumor cells proliferate by supplying nutrition but also secretes various growth factors (hepatocyte growth factor- HGF, fibroblast growth factor- FGF) and cytokines." (PMID 30159133, 2018). "The activation of the HGF/MET signaling axis is reported to be involved in tumor progression, including increased cell-proliferation, motility, invasiveness (epithelial-mesenchymal transition: EMT) and anti-apoptotic potential." (PMID 30469509, 2018). "In MB cells invading collagen gels, we observed increased a-Iß1 in HGF-stimulated cells at the invasion fronts, where Iß1 turnover is important for protrusion extension during growth factor-induced tumor cell migration." (PMID 29796184, 2018). "Growth factors such as epidermal growth factors (EGFs), fibroblast growth factors (FGFs), platelet derived growth factor (PDGF), and hepatocyte growth factor (HGF) are highly abundant in the tumor environment." (PMID 30487436, 2018). "Consistently, depletion of MAP4K4 in MB tumor cells restricts HGF-driven matrix invasion in vitro and brain tissue infiltration ex vivo." (PMID 29796184, 2018). "Studies of the tumor microvasculature in these murine models revealed HGF-dependent dysregulated angiogenesis with tortuous blood vessel formation." (PMID 29996818, 2018). "Among the plethora of factors secreted in the tumor microenvironment, HGF plays a relevant pro-malignant role, triggering cancer cell invasion and metastatic dissemination via paracrine stimulation of its receptor on tumor cells." (PMID 30544501, 2018). "Alternatively, HGF present in the tumor microenvironment activates c-Met receptors displayed on the surface of cancer cells, through the activation of the paracrine signaling system." (PMID 30214428, 2018). "A synergistic inhibition of EOC was also observed in xenograft tumor growth in a nude mouse model, identifying the role of hepatocyte growth factor (HGF)/c-Met pathways in mediating anti-apoptotic signals via AKT in EOC." (PMID 29642900, 2018). "Strategies targeting HGF/c-Met activity have warranted further investigation for their potential in combating the metastatic spread of tumours." (PMID 30314527, 2018). "In recent years, the blockade of HGF-Met signalling has become one such strategy to inhibit tumour invasion and metastasis." (PMID 30314527, 2018). "For example, hepatocyte growth factor (HGF), and transforming growth factor β (TGFβ) are known to enhance tumor cell proliferation and promote the acquisition of invasive phenotypes, such as epithelial-to-mesenchymal transitions (EMT)." (PMID 29732370, 2018). "MET activation further stimulates HGF production by CAFs, thus establishing a dynamic bidirectional ‘tumor-host signaling program’." (PMID 30544501, 2018). "Matriptase plays important roles in both initiating tumor developments by triggering HGF/MET and PAR-2 or PI3K-Akt-mTor mediated signaling as well as tumor progression, including invasiveness and metastasis." (PMID 29899836, 2018).
tumor (continued). "We also demonstrated a critical contribution of CAF-released soluble factors such as hepatocyte growth factor (HGF), basic fibroblast growth factor and transforming growth factor-β in promoting tumor cell migration speed." (PMID 29849946, 2018). "CAFs actively communicated with cancer cells and promoted tumor progression through cytokines such as HGF, IL-6, TGF-β, VEGF, FGF, and CXCL128–10." (PMID 30158543, 2018). "The CD44v6 peptide inhibited c-MET phosphorylation in the primary tumor and HGF and VEGF secretion in L3.6pl cells." (PMID 29747682, 2018). "Here, we highlight the role of TGFβ1 as inducer of tumor cell migration by increasing HGF/MET signaling in vitro." (PMID 30004628, 2018). "Tumor cells can secrete several chemokines, such as CC chemokine ligand 2, soluble colony-stimulating factor 1, stromal cell-derived factor, hepatocyte growth factor, and periostin (POSTN), to recruit TAMs in cancers." (PMID 30034397, 2018). "Several intracellular signals, such as tumor necrosis factor-α, FGF-2, FGF-4, EGF, and HGF enhance TGF-β signaling to promote tumor invasion/metastasis and EMT." (PMID 29758011, 2018). "This was probably as a direct effect of increased tumour volume in these mice, as myeloma tumour cells secrete numerous osteoclast activating factors and osteoblast inhibitory factors, including HGF." (PMID 29924867, 2018). "Matsumoto and Nakamura found that activated CAFs can release the hepatocyte growth factor, which mediates tumor–stromal interactions." (PMID 30355650, 2018). "Accumulating evidence shows that activation of the HGF/c-Met pathway in SCLC cells also leads to increased tumor growth and survival." (PMID 30134579, 2018). "The aim of envisaging a molecule able to specifically recognize VEGF and HGF that are key angiogenic factors was the creation of an innovative tool halting complex processes such as tumor angiogenesis." (PMID 29568363, 2018). "Our observation that fibroblast-derived HGF promotes cancer cell migration in vitro and tumor development in vivo supports the notion that both cancer and stromal miR-16 levels affect cancer aggressiveness." (PMID 29558956, 2018). "Transfection of bone marrow stromal cells with miR-340 generates exosomes capable of inhibiting tumor angiogenesis via the HGF/c-MET signaling pathway in endothelial cells." (PMID 30018618, 2018). "Blocking the HGF/Met pathway by Met inhibitors or monoclonal antibodies strongly inhibits tumor growth and tumorigenicity in many malignancies including HCC." (PMID 29848298, 2018). "The quantification of the area covered by the expanding tumor cells using the anti-human nuclei signal revealed a further increase in expansion in HGF-stimulated DAOY cells, which was abrogated in MAP4K4-depleted cells." (PMID 29796184, 2018). "This over-expression promotes migratory and invasive capabilities of MB tumor cells in response to HGF-c-Met stimulation or photon irradiation." (PMID 29796184, 2018). "Recent work has also indicated that this paracrine signaling is important to sensitize tumor cells to hepatocyte growth factor (HGF) signaling by endothelial cells to attract them towards blood vessels." (PMID 29636067, 2018). "C-Met expression is found in HL, NPC, and EBV+ GC, while its ligand hepatocyte growth factor (HGF) is produced in dendritic cells in HL and in the interstitial tissue surrounding the tumor in NPC." (PMID 29652813, 2018). "It has been shown that VEGF mRNA expression was mainly targeted to primary colorectal tumor cells whereas angiopoietin-2 and HGF mRNA expression was targeted to tumor-adjacent stromal cells." (PMID 30598022, 2018). "Tumor-associated fibroblasts (TAFs) promote tumor development by secreting cytokines as VEGF, IL-6, and HGF, that are responsible by the induction of the tumor vascularization and subsequently stimulate cell proliferation." (PMID 30304861, 2018).
tumor (continued). "The HGF/c-Met axis, which can interact and cooperate with other types of tyrosine kinases, can stimulate various downstream signaling pathways in tumor cells, such as PI3K/AKT, JAK/STAT, Ras/MAPK, SRC, and Wnt/β-catenin, among others." (PMID 29455668, 2018). "HGF from fibroblasts and c-Met from tumor cells formed a signaling pathway, which was intensely correlated with proliferation, metastasis, and angiogenesis." (PMID 30158543, 2018). "Independent studies before cloning of the HGF gene identified the same molecule as a potent inducer of epithelial cell motility (and thus termed as scatter factor) and as a fibroblast-derived cytotoxic factor for some tumor cell lines." (PMID 29616031, 2018). "When rapid tumor growth depletes local blood supply, long-term adaptation to hypoxia occurs through angiogenesis promoted by the HGF/MET axis." (PMID 30208970, 2018). "HGF is a multifunctional growth factor reported to have an important role in tumor progression through its specific receptor tyrosine kinase MET, the c-met proto-oncogene product." (PMID 30469509, 2018). "When aberrantly activated, MET and its stroma-secreted ligand HGF (Hepatocyte Growth Factor) concur to tumor onset, progression, and metastasis in solid tumors, thus representing a relevant target for cancer precision medicine." (PMID 30544501, 2018). "Baseline angioprotein-1 and hepatocyte growth factor (HGF) significantly correlated with the gross tumor volume." (PMID 29398577, 2018). "Using a phospho-RTK array, we found that c-MET acts upstream of Akt, indicating that LAMB3 leads to tumor invasion via Akt activation induced by the HGF/c-MET axis in PTCs." (PMID 29426928, 2018). "HGF inhibition by means of neutralizing antibody (AMG102) inhibited tumor growth and metastasis as compared to gemcitabine treatment." (PMID 30567565, 2018). "While researchers are currently investigating the relationship between HGF and cancer, some properties of HGF in the tumor microenvironment should be considered." (PMID 30214428, 2018). "Their data indicated the importance of targeting the tumor microenvironment by blocking epigenetic mechanisms, which control critical events for colonization such as HGF/c-Met axis as a potential therapy of bone metastasis." (PMID 29455657, 2018). "Together, these results revealed that CUX1/FGF1/HGF signalling is the main target of DPPA in the inhibition of tumour angiogenesis." (PMID 30010249, 2018). "The hepatocyte growth factor (HGF) produced by tumor and stromal cells acts as a multifunctional cytokine and activates the c-MET receptor, which is expressed in different tumor cell types." (PMID 30352967, 2018). "The sustained directionality of tumor cells to a vessel is promoted by a chemotactic gradient of hepatocyte growth factor (HGF) produced from vessel endothelium." (PMID 29983921, 2018). "Recent studies showed that mice with reduced levels of matriptase display a significant delay in mammary tumor formation and blunted tumor growth mediated through the HGF/MET axis." (PMID 29899836, 2018). "The MET/HGF pathway is involved in the complex crosstalk between tumor and stroma, in particular in the interaction between cancer cells and activated PSCs." (PMID 30544501, 2018). "Bivalent antibodies have shown promising potential as biological therapeutics capable of inhibiting tumor growth driven by elevated HGF as well as by constitutive activation of c-MET through overexpression, gene amplification, or genetic mutation." (PMID 29725606, 2018). "The hepatocyte growth factor (HGF) is another major player promoting tumor growth as well as metastasis formation." (PMID 30004628, 2018). "It has been determined that c-Met gene mutations, overexpression, and amplification also occur in a variety of human tumor types, and these events are closely related to the aberrant activation of the HGF/c-Met signaling pathway." (PMID 29455668, 2018).